TIMP1 (TIMP metallopeptidase inhibitor 1)
Diseases named in the same sentence as TIMP1 in open-access papers (continued):
Sharing a sentence is not in itself a finding about the gene and the disease.
Insulin resistance (14 papers, 2010 to 2026). Increased resistance towards insulin, that is, diminished effectiveness of insulin in reducing blood glucose levels. "In this study, we examined associations between MMP-2 -1306 C/T (rs243865) and MMP-9 -1562 C/T (rs3918242) single-nucleotide polymorphisms, serum levels of MMP-2, MMP-9 and TIMP-1, and the occurrence of insulin resistance in patients in a Polish cohort." (PMID 41828387, 2026). "OSM treatment regulates the expression of many proinflammatory adipokines causing insulin resistance (Timp1, PAI-1, Igfbp3, and Spp1) in adipose tissue." (PMID 31576964, 2020). "Furthermore, a murine model of hyperinsulinaemia and insulin resistance is associated with increased TIMP-1 and -2 levels, suggesting that insulin homeostasis may affect extracellular matrix metabolism via TIMP-mediated processes." (PMID 20565712, 2010). "The role of TIMP-1 in liver metabolism, insulin resistance and inflammation remains to be elucidated." (PMID 26168159, 2015). "In addition, Elks CM and colleagues also observed that treatment with oncostatin M induced gene expression of Timp1, Igfbp3, and Spp1 while alleviating insulin resistance." (PMID 38397957, 2024). "This suggests that TIMP-1 might promote accumulation of hepatic triglycerides and hepatic insulin resistance." (PMID 26168159, 2015). "In addition, MMP9, TIMP1, SPP1 and POSTN were shown to play a role in regulating fat metabolism and insulin resistance." (PMID 35966072, 2022). "The significant correlation between circulating levels of TIMP-1 to insulin, and HOMA2-IR, might nevertheless, reflect that remodeling in AT is related to insulin resistance and MetS." (PMID 31890043, 2019). "Here we show that inflammatory biomarkers sTNFRII, sICAM-1 and TIMP-1 significantly (P < 0.05) correlate with insulin resistance in Healthy, Non-DM, and Pre-DM individuals indicating early chronic inflammation could be associated with the development of diabetes." (PMID 31178745, 2019).
ischemia (14 papers, 2009 to 2025). A hypoperfusion of the BLOOD through an organ or tissue caused by a PATHOLOGIC CONSTRICTION or obstruction of its BLOOD VESSELS, or an absence of BLOOD CIRCULATION. "Another study has shown that early exercise obviously weakens the ischemia‐mediated upregulation of TIMP1, thereby ameliorating ischemic brain damage." (PMID 39364701, 2024). "The right atrial activity of reperfused myocardium was followed, showing a rapid increase in MMP2 and MMP9 activity accompanied by a rapid decrease in TIMP1, demonstrating global alteration of left ventricular function and persistence of ischemia." (PMID 37512106, 2023). "After ischemia, upregulated expression of tissue inhibitors TIMP1, TIMP2, TIMP3 and CTGF was observed in both the necrotic and salvaged myocardium." (PMID 32727469, 2020). "Though 14,15 EET application showed only a little influence on MMP expression compared to ischemia, it significantly lowered TIMP1 expression on day 6 compared to ischemia and on day 9 compared to 11,12 EET." (PMID 30650075, 2019). "The concomitant changes in expression of metalloproteinases and their endogenous inhibitors have been described in TBI and in ischemia, consistent with the increase in TIMP-1 we observed in response to albumin." (PMID 22507553, 2012). "Timp1 has been shown to be upregulated following focal ischemia, a process that could be part of a general neuronal response that mediates tissue reorganization." (PMID 28290150, 2018). "Molecular analysis revealed an increase in TIMP1, TIMP2, and TIMP3 mRNA expression soon after ischemia onset in the whole area at risk, while no variations in the evaluated MMPs were observed." (PMID 32727469, 2020). "In contrast to this findings, 11,12 EET application seemed to enhanced level of TIMP1 expression on day 3 and day 9 compared to control and ischemia though this was not significant." (PMID 30650075, 2019). "The data indicated that early exercise significantly inhibited the ischemia-induced reduction of occludin, and an increase in MMP-9 promoted TIMP-1 expression (p < 0.01), attenuated the BBB disruption (p < 0.05) and neurological deficits (p < 0.01) and diminished the infarct volume (p < 0.01)." (PMID 23708107, 2013). "Moreover, regardless of rtPA treatment, otaplimastat restored TIMP1 expression lowered by embolic ischemia (data not shown)." (PMID 35163322, 2022). "However, administration of U0126 beginning 12 hours after reperfusion did not significantly reduce the ischemia-induced expression of MMP-9 or TIMP-1 in the cerebral vessel smooth muscle cells." (PMID 19497125, 2009).
ulcer (14 papers, 2008 to 2025). "This disparity in the ratio between MMPs and TIMP-1 contributes to the development of chronic ulcers, and a deficiency in the expression of MMPs can hinder the proper and timely healing of ulcers." (PMID 38254696, 2024). "In other words, hMPs spraying is believed to maintain the balance between TIMP-1 and MMPs, resulting in ulcer healing with reduced fibrosis and stricture prevention by inhibiting excessive contraction." (PMID 39404963, 2025). "Topical APG significantly reduced ulcer area and improved proteolytic balance by lowering MMPs and increasing TIMP-1." (PMID 41245602, 2025). "There is a sharp contrast between the Mmp9 and Timp1 ratios of the two ulcer models in C57BL/6 J mice." (PMID 35386010, 2022). "The MMP-9 and TIMP-1 levels in ulcers were higher than in the chronic superficial gastritis specimens." (PMID 35163805, 2022). "An equilibrium between Mmps and Timps is fundamental for ulcer healing, and the Mmp9/Timp1 serum level ratio has been shown to be an indicator of healing, with increased levels of Mmp9 predicting poor wound healing in human diabetic patients." (PMID 35386010, 2022). "Mmp9 is a main effector of the ulcer response, and as shown in the PrU network, it corresponds to an increase of Timp1 and Timp2, the two main inhibitors of metalloproteinases." (PMID 35386010, 2022). "Gastric ulcer tissues with a combined pattern of MMP-9 ≥3 and TIMP-1 ≥2 in ulcer epithelial cells and MMP-9 ≥ 4 in the ulcer inflammatory cells significantly defined the “H." (PMID 22645431, 2012). "In summary, H. pylori-infected gastric ulcers express higher MMP-9 and TIMP-1 than NSAID-related ulcers." (PMID 22645431, 2012). "H. pylori-infected gastric ulcers express higher MMP-7, MMP-9, and TIMP-1 than NSAID-related ulcers." (PMID 22645431, 2012). "On the other hand, it will be interested to compare MMP and TIMP-1 expressions in the middle or final stage of the healing process between H. pylori-infected ulcers and NSAID-related ulcers." (PMID 22645431, 2012). "As such, this study surveyed if the H. pylori dupA genotype and certain SNP genotypes of MMP-3, MMP-7, MMP-9, TIMP-1, and TIMP-2 predispose H. pylori-infected Taiwanese patients to ulcer risks." (PMID 20707923, 2010). "It has also been demonstrated that in IBD, TIMP-1 is expressed by inflammatory cells, fibroblasts and vascular smooth muscle cells most prominently in actively inflamed areas in ulcer bases." (PMID 19036126, 2008). "They observed that the variations in the levels of MMPs and TIMP-1 were similar during the healing process of the ulcer; their levels increased rapidly after the injury occurrence, reached the highest after one week, and constantly reduced through the last phase of tissue repair." (PMID 37605137, 2023). "Our study further validated the difference of MMP-9 and TIMP-1 expression on the ulcer etiology." (PMID 22645431, 2012). "In addition, the upregulation of MMP-3 in inflammatory cells of ulcer tissues is similar to TIMP-1." (PMID 22645431, 2012). "This study investigated if the H. pylori dupA genotype and certain host single nucleotide polymorphisms (SNPs) of matrix metalloproteinases (MMPs) and their inhibitors (TIMPs), including MMP-3, MMP-7, MMP-9, TIMP-1 and TIMP-2, might correlate with ulcer risk of H. pylori-infected Taiwanese patients." (PMID 20707923, 2010). "pylori-infected” ulcer were 2.5 for MMP-9 (area of ROC curve [AUC] 0.68, 95% CI: 0.56–0.81, P = 0.007) and 1.5 for TIMP-1 (AUC 0.74, 95% CI: 0.63–0.85, P = 0.001) over gastric ulcer epithelial cells, respectively." (PMID 22645431, 2012). "TGF-β1 regulates TIMP-1 so that the levels of TIMP-1 increase and the overexpressed MMP-9 is inhibited by TIMP-1.22The clinical use of PRP in traumatic ulcers can be advantageous and disadvantageous during the ulcer healing process." (PMID 37172947, 2024).
ulcer (continued). "We stained for inflammatory fibroblast markers, CHI3L1 and TIMP1, together with pan-fibroblast marker fibroblast activation protein (FAP) and discovered elevated numbers of triple-positive cells within the ulcer area of healing DFUs, with the cells forming dense aggregates." (PMID 35013299, 2022). "Based on the predominant ulcer location over the antrum and the weaker MMP-9 and TIMP-1 expressions in gastric ulcer tissues, gastric ulcers in H. pylori-infected NSAID users may be predominantly similar to those in NSAID use." (PMID 22645431, 2012). "Moreover, in the NSAID-related group and the combined H. pylori-infection and NSAID-use group, MMP-3, MMP-9, and TIMP-1 expression over inflammatory cells of the lamina propria of ulcer tissues were higher than in nonulcer tissues (P < 0.05)." (PMID 22645431, 2012). "However, in ulcer tissues, inflammatory cells had higher TIMP-1 upregulation than in nonulcer tissues, especially in the NSAID-related group and in the combined H. pylori-infection and NSAID-use group (P = 0.009 and 0.005, resp.)." (PMID 22645431, 2012). "Non-healed ulcers exhibit elevated levels of MMP-1, -2, -8, and -9, while showing lower levels of TIMP-1." (PMID 38254696, 2024). "IHC has shown that H. pylori–related gastric ulcers express significantly higher levels of MMP-7, MMP-9 and TIMP-1 in comparison to undamaged tissue and NSAID (nonsteroidal anti-inflammatory drug)-related ulcer tissue." (PMID 35163805, 2022).
viral infection (14 papers, 2004 to 2025). "This correlation suggests that in the disease state, both MMP-3 and TIMP-1 are upregulated in tandem, possibly reflecting a coordinated response to viral infection and inflammation in ARN." (PMID 39723192, 2024). "TIMP-1 was also significantly upregulated in response to viral infection and Poly I:C at 48 and 72 HPI." (PMID 30442185, 2018). "We have two hypotheses: the innate immune response following viral infection and TIMP-1-secreting cells." (PMID 36670630, 2022). "The viral infection rate in EGFP-CA16 + MMP9 monkeys was higher than that in EGFP-CA16 monkeys and further higher than that in EGFP-CA16 + TIMP-1 monkeys." (PMID 30228270, 2018). "The viral infection rates of brain tissues and viral genomic copies in EGFP-CA16 + MMP9 monkeys were the highest, followed by those in EGFP-CA16 monkeys, and they were the lowest in EGFP-CA16 + TIMP-1 monkeys." (PMID 30228270, 2018).
Arthritis (13 papers, 2005 to 2025). Inflammation of a joint. "The underlying mechanism causing reduced arthritis may be linked to the complex regulatory network of TIMP-1 and appears to be independent from the local iron levels, oxidative stress and ferroptosis in the synovial tissues." (PMID 39513899, 2024). "The dynamic balance between MMP-3 and TIMP-1 determines the direction of cartilage metabolism, and monitoring their levels helps assess arthritis severity and treatment efficacy." (PMID 41458513, 2025). "Changes occurring following castration that were independent of testosterone included BALF levels of TNF-α and CXCL2, lung levels of MMP-8, TIMP-1, and C5a, and lung autoantigen expression as well as lung cellular infiltrates and arthritis severity." (PMID 38086040, 2024). "We stimulated TNFα-pretreated OA- and RA-SF with 10–11 to 10–14 M PK2 and measured the cell culture medium concentration of the arthritis-aggravating factors IL-6 and MMP-3 and arthritis-inhibiting factors TIMP-1 and OPG." (PMID 34526577, 2021). "Our predictions are supported by experimental data showing limited benefit from overexpressing TIMP-1 in a mouse model of arthritis." (PMID 24757149, 2014). "In murine AIA, significant and temporal changes in cytokines (IL-1β, TNFα, IFN-γ, IL-6) and factors that govern extracellular matrix turnover (MMP-3, MMP-13, TIMP-1) occur during the acute phase, Days 1 to 3 after arthritis induction." (PMID 20307272, 2010). "In contrast, levels of TIMP1 in the EF group increased to varying degrees, which indicated that EF could improve arthritis." (PMID 34742322, 2021). "In addition, the quantative expression profiling of MMP-3, tissue inhibitor of metalloproteinases 1 (TIMP-1) and MMP1/TIMP1 complex, which are mainly implicated in the pathogenesis of arthritis, was also carried out through ELISA." (PMID 21593968, 2008). "Moreover, the expression of TIMP-1 at day 7 after arthritis onset was significantly higher in p47phox-/- mice than in the WT controls." (PMID 15987491, 2005). "The expression of TIMP mRNA was determined in WT controls and p47phox-/- mice: TIMP-1 and TIMP-2 were moderately expressed after the induction of arthritis in both groups." (PMID 15987491, 2005).
atrial fibrillation (13 papers, 2011 to 2025). A disorder characterized by an electrocardiographic finding of a supraventricular arrhythmia characterized by the replacement of consistent P waves by rapid oscillations or fibrillatory waves that vary in size, shape and timing and are accompanied by an irregular ventricular response. "In our study higher TIMP-1 levels (>124.9 ng/mL) were associated with higher NT-proBNP levels, a greater prevalence of atrial fibrillation, reduced exercise capacity, and larger right ventricular size." (PMID 39334904, 2024). "Soluble suppression of tumorigenicity 2 protein (sST2) and tissue inhibitor of matrix metalloproteinase (TIMP)-1 are involved in multiple pathogenic pathways, including cardiac remodeling, which is the main pathology of atrial fibrillation (AF)." (PMID 36683600, 2022). "Atrial fibrillation was more prevalent in patients with elevated TIMP-1 levels (27.6% vs. 13.1%, p = 0.04)." (PMID 39334904, 2024). "High TIMP-1 levels (>124.9 ng/mL) correlated with elevated NT-proBNP, more atrial fibrillation, reduced exercise capacity, and larger right ventricles." (PMID 39334904, 2024). "In addition, TIMP1 expression can also predict new postoperative atrial fibrillation." (PMID 40432920, 2025). "Contrarily, in the group of patients with postoperative atrial fibrillation (POAF) after primary coronary artery by-pass grafting, the level of MMP-9 was decreased and TIMP-1 level increased." (PMID 36835040, 2023). "It was also observed that TIMP-1 and PICP levels were significantly higher in MS and MR subjects respectively with atrial fibrillation (p<0.05)." (PMID 24603967, 2014). "A cohort study including paroxysmal (<7 days) versus persistent (>7 days) atrial fibrillation patients proved that altered expression of TGFβ1, MMP-9, and tissue inhibitor of metalloproteinase-1 (TIMP-1) plays a vital role during fibrosis progression, whereas IL-6 contributes to inflammation events." (PMID 37569677, 2023). "Atrial fibrillation patients with severe aortic stenosis present increased atrial fibrosis and collagen type III synthesis, with extracellular matrix remodelling demonstrated by a decrease in the MMP16/TIMP4 ratio, along with an increased serum TIMP1 and TIMP2 proteins." (PMID 33129260, 2020).
chronic pancreatitis (13 papers, 1996 to 2024). A chronic inflammatory process causing damage and fibrosis of the pancreatic parenchyma. "None of the three molecules were elevated in the plasma of mice with caerulein‐induced chronic pancreatitis after 7 weeks of treatments confirming the specific association of high levels of TIMP1, MMP7, and TSP2 with neoplastic transformation." (PMID 29941541, 2018). "These authors studied the possibility of implementing a diagnostic algorithm using CA19-9, OPN, and TIMP1 and found a diagnostic accuracy of 89.5% in differentiating patients with pancreatic adenocarcinoma, patients with chronic pancreatitis, and healthy people." (PMID 35454771, 2022). "A second confirmatory phase on an independent cohort of 131 PDAC patients, 30 chronic pancreatitis patients, and 131 healthy subjects confirmed the PDAC association for MMP7, CCN2, IGFBP2, TSP2, sICAM1, TIMP1, and PLG." (PMID 29941541, 2018). "Building on previous study results, a more recent study showed that TIMP-1 levels are increased both in the blood and pancreas in mouse models with premalignant pancreatic lesions, such as chronic pancreatitis, pancreatic intraepithelial neoplasia (PanIN) and PDAC." (PMID 35740692, 2022). "Furthermore, the presence of increased TIMP-1 in pre-malignant lesions, such as chronic pancreatitis, raises the question as to how early pre-metastatic niche formation starts." (PMID 35740692, 2022). "This study seems to deliver a partial answer as to how increased TIMP-1 levels observed in conditions such as chronic pancreatitis and PanIN may reinforce inflammatory changes within the liver, which later contribute to metastatic outgrowth." (PMID 35740692, 2022). "Furthermore, Poruk and colleagues have demonstrated the utility of measuring systemic TIMP-1 levels as a diagnostic tool to distinguish early, resectable PDAC from healthy tissue and chronic pancreatitis." (PMID 29903049, 2018). "In experimental mouse models of chronic pancreatitis (CP), TIMP-1 mRNA expression in the pancreas increases with disease progression, suggesting an important role of TIMP-1 in pancreatic fibrosis." (PMID 29394913, 2018). "Plasma TIMP-1 was measured by ELISA in patients diagnosed with PDAC (n = 36) and chronic pancreatitis (CP) (n = 25)." (PMID 29394913, 2018). "Performance of the markers distinguishing PDAC from controls and chronic pancreatitis revealed statistically significant biomarker candidates ALCAM1, TIMP1, ICAM1, REG3, IGFBP4 panel plus CA19-9." (PMID 29518918, 2018). "TIMP1 had an AUC of 0.83 (95% CI 0.77 to 0.89) comparing patients with early stage PDAC to healthy controls and AUC of 0.68 (95% CI 0.59 to 0.78) when compared with patients with chronic pancreatitis." (PMID 38123998, 2024). "TIMP-1 is already produced and secreted into the circulation by pancreatic premalignant lesions, and even patients with chronic pancreatitis, an inflammatory lesion from which PDAC may also develop, exhibit upregulated expression of TIMP-1." (PMID 29903049, 2018). "Indeed, TIMP-1 protein performance as a blood-based biomarker in PDAC has been shown to be impaired in patients with jaundice, though not in patients with chronic pancreatitis." (PMID 36969742, 2022).